TGFBI (transforming growth factor beta induced)
Diseases named in the same sentence as TGFBI in open-access papers (continued):
Sharing a sentence is not in itself a finding about the gene and the disease.
cancer (continued). "On the basis of these results, we hypothesized that in CRC, TGFBI levels are maintained through TGFβ signaling in stromal cells, whereas in CRC-LM, TGFBI is also directly secreted by cancer cells that can respond to TGFβ stimulation." (PMID 33408771, 2021). "Correlational analysis of clinical OSCC datasets with TGFβ axis differentially expressed genes revealed that the summed expression of FN1, TGFB2, TGFBR2, and TGFBI, dubbed as the CAF index, is a powerful predictor in dichotomized survival analysis for patients of diverse cancer subtypes." (PMID 32605311, 2020). "Similarly, TGF-β-induced protein (TGFBI)—a downstream component of the TGF-β signaling pathway—has been shown to promote and/or inhibit cancer." (PMID 28106769, 2017). "Since SPARC regulates TGFBI deposition in the ECM, we determined how the Met5A-derived ECM could influence cancer cell motility and response to paclitaxel." (PMID 27622658, 2016). "However, there is still no pan-cancer information about the roles of TGFBI in various types of cancer based on large clinical datasets." (PMID 34671645, 2021). "However, there are no previous pan-cancer studies on the relationship between TGFBI expression and various tumors." (PMID 34671645, 2021). "Overlapping molecules in two groups included up-regulated transforming growth factor beta induced (TGFBI) and Nestin (NES); and down-regulated synuclein alpha (SNCA) and heat shock protein family A member 12A (HSPA12A), which have demonstrated roles in GBM and/or other cancers." (PMID 29228611, 2017). "However, there is currently no pan-cancer evidence regarding TGFBI." (PMID 34671645, 2021). "For the comparison of all UCa patients vs. those with other cancers and no cancer at all, we obtained an AUC of 0.77 (95% CI 0.71–0.83) for CXCL16 and an AUC of 0.77 (95% CI 0.71–0.84) for TGFBI." (PMID 39587670, 2024). "For example, many of the cancer cells in HNSCC express SNAI2, while only few of those cells express a full pEMT program that includes TGFBI, SERPINE1 and other ESGs, but not higher SNAI2 levels." (PMID 33972543, 2021).
infection (13 papers, 2013 to 2025). The state of being infected such as from the introduction of a foreign agent such as serum, vaccine, antigenic substance or organism. "To assess whether the EBV-associated increase in DNA methylation at TGFBI sites may impact its gene expression, we monitored its mRNA expression throughout the course of infection." (PMID 35267594, 2022). "For this, primary B cells isolated from three independent donors were infected in vitro with EBV and then harvested at different time points during the infection until cell immortalization, followed by TGFBI mRNA expression levels analysis (RT-qPCR)." (PMID 35267594, 2022). "We found that upon infection, the level of TGFBI expression is drastically reduced, and the downregulation is maintained in LCL cells originating from the EBV-induced immortalization of B cells." (PMID 35267594, 2022). "As expected, lenti-shTGFBI infection of THP-1 cells resulted in significant downregulation of TGFBI expression and impaired the PMA-induced macrophage-like differentiation as revealed by the decreased mRNA expression of differentiation markers (CD11b and CD14) compared with the lenti-ctrl infection." (PMID 33128580, 2021). "Further studies are warranted to determine whether plasma TGFBI and CSF1R are associated with infection/inflammation-related preterm birth, given the exclusion of women with infectious and inflammatory etiologies of SPTB in the present study." (PMID 34710180, 2021). "The derived immortalized LCL cells were then subjected to RT-qPCR to evaluate TGFBI mRNA expression levels as well as the expression of the viral genes LMP1 and BLZF1 (to assess the infection status in the presence of AFB1)." (PMID 35267594, 2022). "While it is already established that AFB1 impacts EBV infection efficiency and subsequent cell transformation, here we show for the first time that, apart from favoring the infection outcomes, AFB1 and EBV share TGFBI as a molecular target." (PMID 35267594, 2022).
adenocarcinoma (6 papers, 2008 to 2024). A common cancer characterized by the presence of malignant glandular cells. "TGFBI encodes a 68-kDa secretory protein induced by transforming growth factor-β (TGF-β) in human adenocarcinoma cells as well as other human cell types." (PMID 31277676, 2019). "The TGFBI was firstly identified as a novel gene in the human adenocarcinoma cell line A549 after treatment with transforming growth factor-beta (TGF-β)." (PMID 38395907, 2024).
gastrointestinal tract cancers (5 papers, 2015 to 2022). "An upregulation of TGFBI was observed in gastrointestinal tract cancers and resulted in activation of the FAK/AKT/AKT1S1/PRS6/EIF4EBP pathway, playing a role in cell survival and proliferation." (PMID 33921897, 2021). "Our data suggest that TGFBI functions as a promoter of certain gastrointestinal tract cancers." (PMID 25889002, 2015). "Thus, TGFBI functions as a promoter of certain gastrointestinal tract cancers." (PMID 25889002, 2015).
autosomal dominant disease (4 papers, 2017 to 2023). Autosomal dominant form of disease. "Reis–Bücklers corneal dystrophy (RBCD) is a bilateral and autosomal dominant disease caused by a mutation in keratoepithilin, i.e., BIGH3, also known as transforming human growth factor (TGFBI), on chromosome 5q." (PMID 36977302, 2023).
cardiac disease (2 papers, 2017 to 2024). "Additionally, TGFBI has been found as an upstream regulator of mTOR activation in Drosophila models of cardiac disease." (PMID 39041002, 2024). "In the current study we investigate the role of the matricellular protein, transforming growth factor beta-induced (TGFBI), which is induced in various forms of heart disease." (PMID 28750100, 2017).
degenerative diseases (2 papers, 2013 to 2025). "In degenerative diseases, the interaction of TGFBI with extracellular matrix components and its role in cellular senescence highlight its involvement in disease progression and tissue degeneration." (PMID 39752341, 2025).
head and neck tumor (1 paper, 2019). "IHC database showed the protein expression of TGFBI, SPP1, and LAMB3 in head and neck tumor tissues were up-regulated compared with normal tissues." (PMID 31485443, 2019).
metabolic disorders (1 paper, 2023). "In summary, the present study revealed that the deletion of the ECM protein TGFBI has a protective effect against HFD-induced metabolic disorders." (PMID 36854775, 2023). "Proteins that influence adipose microenvironment can be involved in metabolic diseases, so Seul Gi Lee and Ju-Ock Nam at Kyungpook National University, Taeg Kyu Kwon at Keimyung University, both in Daegu, South Korea, and co-workers investigated how TGFBI affects adipose metabolism in a mouse model." (PMID 36854775, 2023).
TGFBI also shares sentences with these, for which no sentence is quoted: epithelial basement membrane dystrophy (6 papers); lymphoma (4); rheumatoid arthritis (4); stromal corneal dystrophies (4); type 2 diabetes (3); Arthritis (2); bacterial infection (2); corneal amyloidosis (2); endocervical adenocarcinoma (2); gastric tumors (2); leukaemias (2); macular corneal dystrophy (2); myopathies (2); pancreatic adenocarcinoma (2); posterior polymorphous corneal dystrophy 3 (2); serous ovarian carcinoma (2); Amoebiasis (1); Anterior polar cataract (1); aortic aneurysm (1); asthma (1); astrocytoma (1); atrial fibrillation (1); Axenfeld-Rieger syndrome type 3 (1); benign adenoma (1); benign ovarian tumors (1); blood cancer (1); brittle cornea syndrome (1); cardiovascular disease (1); cervical tumours (1); chondrosarcoma (1).
A further 55 diseases each share a sentence with TGFBI in 1 paper.